ZNF174 (zinc finger protein 174)
Description:
Transcriptional repressor.
Synonyms: ZSCAN8
Tractability: Small molecule: it has a binding pocket of medium quality. PROTAC: UniProt records ubiquitination sites on it; ubiquitination databases record sites on it.
Gene: Protein-coding gene on chromosome 16 (3,401,215 to 3,409,364, forward strand). Ensembl gene ENSG00000103343.
Subcellular location: Nucleus
Subcellular location (Human Protein Atlas): Nucleoli fibrillar center; Nuclear bodies
Gene Ontology:
Molecular function: DNA-binding transcription factor activity; protein binding; protein homodimerization activity; sequence-specific DNA binding; sequence-specific double-stranded DNA binding; transcription cis-regulatory region binding; DNA-binding transcription factor activity, RNA polymerase II-specific; RNA polymerase II cis-regulatory region sequence-specific DNA binding
Biological process: negative regulation of DNA-templated transcription; negative regulation of transcription by RNA polymerase II; regulation of transcription by RNA polymerase II
Cellular component: fibrillar center; nuclear body; chromatin; nucleus
Genetic constraint (gnomAD): Loss-of-function variants: 25 observed, 36.42 expected, observed/expected ratio (o/e) 0.69, 90% interval 0.5 to 0.96. The upper end of that interval is the gene's LOEUF score, 0.96, which puts it in group 4 of 6, group 1 being the genes least tolerant of losing a copy. Missense variants: 415 observed, 445.3 expected, observed/expected ratio (o/e) 0.93, 90% interval 0.86 to 1.01. Synonymous variants: 163 observed, 166.77 expected, observed/expected ratio (o/e) 0.98, 90% interval 0.86 to 1.11.
Homologues: Orthologues: chimpanzee ZNF174 (99% identical), macaque ZNF174 (99% identical), dog ZNF174 (88% identical), guinea pig ZNF174 (86% identical), pig ZNF174 (86% identical), rabbit ZNF174 (83% identical), rat Zfp174 (76% identical), mouse Zfp174 (75% identical), Drosophila melanogaster CG12391 (17% identical), zebrafish plagl2 (13% identical), zebrafish ovol1b (13% identical), zebrafish ovol1a (13% identical), and 5 more. Paralogues in human: ZSCAN29 (33% identical), ZKSCAN2 (33% identical), ZSCAN32 (31% identical), ZNF18 (30% identical), ZSCAN5C (30% identical), ZNF202 (29% identical), ZSCAN5B (29% identical), ZNF274 (28% identical), ZSCAN5A (28% identical), ZNF496 (27% identical), ZNF446 (26% identical), ZNF444 (22% identical), and 17 more.